RN7SL79P (RNA, 7SL, cytoplasmic 79, pseudogene)
Gene: Miscellaneous RNA gene on chromosome 17 (31,465,543 to 31,465,832, forward strand). Ensembl gene ENSG00000239595.
Homologues: Orthologues: chimpanzee Metazoa_SRP (99% identical), macaque Metazoa_SRP (95% identical). Paralogues in human: RN7SL1 (84% identical), RN7SL2 (84% identical), RN7SL3 (83% identical), RN7SL664P (80% identical), RN7SL769P (80% identical), RN7SL220P (80% identical), RN7SL543P (80% identical), RN7SL655P (80% identical), RN7SL186P (79% identical), RN7SL296P (79% identical), RN7SL45P (79% identical), RN7SL492P (79% identical), and 703 more.